ITGB6 (integrin subunit beta 6)
Diseases named in the same sentence as ITGB6 in open-access papers (continued):
Sharing a sentence is not in itself a finding about the gene and the disease.
COVID-19 (1 paper, 2023). A disease caused by infection with severe acute respiratory syndrome coronavirus 2. "In particular, we found an association between plasma proteins elevated in severe COVID-19, such as HGF, AREG, CKAP4, S100A12, NCF2, ITGB6, and a subpopulation of monocytes with lower expression of CD86 and HLA-DR, which are characteristics of myeloid-derived suppressor-like cells." (PMID 36829233, 2023). "Among these proteins, KRT19, TOP2B, AREG, HGF, CKAP4, ITGB6, and NCF2 had a higher expression (> twofold) in plasma samples of severe compared to moderate COVID-19 patients, whereas CLEC4C and LTA were among the few proteins that were expressed at lower levels in severe patients." (PMID 36829233, 2023).
Duchenne muscular dystrophy (1 paper, 2014). Duchenne muscular dystrophy (DMD) is a neuromuscular disease characterized by rapidly progressive muscle weakness and wasting due to degeneration of skeletal, smooth and cardiac muscle. "We therefore examined ITGB6 expression in the muscles of the Dystrophin mutant mdx mouse, a genetic model of Duchenne Muscular Dystrophy." (PMID 24488487, 2014). "Excessive TGFβ signaling is thought to contribute to detrimental changes in muscle functional properties in diseases like Duchenne Muscular Dystrophy and therefore regulation of ITGB6 activity may represent a fruitful area for drug discovery research." (PMID 24488487, 2014).
focal segmental glomerulosclerosis (1 paper, 2021). A renal disorder characterized by sclerotic lesions in the glomeruli. "Focal segmental glomerulosclerosis and CAKUT were described in junctional EB with ITGB6 and ITGB4 mutations leading to abnormal integrin β6 and β4 subunits." (PMID 34123558, 2021).
head and neck squamous cell carcinoma (1 paper, 2024). A squamous cell carcinoma that arises from any of the following anatomic sites: lip and oral cavity, nasal cavity, paranasal sinuses, pharynx, larynx, and salivary glands. "The ITGB6 (β6 integrin subunit) proteomic expression profile was analyzed in 71 normal tissues and 108 head and neck squamous cell carcinoma (HNSCC) primary tumors from CPTAC data, using the UALCAN data box-plot analysis portal." (PMID 38951897, 2024).
Hyperglycemia (1 paper, 2025). An increased concentration of glucose in the blood. "In our experiments, the expression of ITGB6 and LTBP1 increased in a time-dependent manner under high-glucose conditions, reinforcing their potential roles in hyperglycemia-induced injury." (PMID 41244197, 2025).
liver cirrhosis (1 paper, 2020). "In summary, MFBs induced the metaplasia of mature hepatocytes into ductal BECs via laminin-ITGB6 signal pathway during the process of liver cirrhosis." (PMID 32251270, 2020).
lung injury (1 paper, 2012). "The protease-activated receptor 1-mediated enhancement of Itgb6-dependent TGF-beta activation has been proposed to represent one mechanism by which activation of the coagulation cascade contributes to the development of acute lung injury." (PMID 22905720, 2012).
mastitis (1 paper, 2016). Inflammation of breast tissue during lactation or postpartum due to an obstructed duct or infection. "Integrin Subunit Beta 6 (ITGB6), which retained intron 15 in the mastitic tissue, was found to be differentially expressed in mastitis-resistant and susceptible sheep infected with Staph. epidermidis." (PMID 27459697, 2016). "The predicted protein structure of the novel transcript ITGB6 was altered because of intron retention; as a result, the function of ITGB6 was affected and risk of mastitis was increased." (PMID 27459697, 2016). "Some immune-related genes, such as ITGB6, MYD88, ADA, ACKR1, and TNFRSF1B, and their potential relationships with mastitis were highlighted." (PMID 27459697, 2016).
myocarditis (1 paper, 2025). Myocarditis is a condition that is characterized by inflammation of the heart muscle (myocardium). "Myocarditis sera induced CAMTA2, ITGB6, NFATC2, and XDH gene expression significantly (p <0.05) above healthy sera." (PMID 40181955, 2025).
periodontitis (1 paper, 2022). An acute or chronic inflammatory process that affects the tissues that surround and support the teeth. "The reciprocal action of STAT3 and FOXO1 on ITGB6 downregulation was also confirmed by the immunostaining of the inflammatory epithelium associated with periodontitis." (PMID 36299623, 2022). "Dysbiotic bacterial dental plaque biofilms are considered the main cause of periodontitis and ITGB6 suppression." (PMID 36299623, 2022). "Integrin β6 (ITGB6), an epithelial-specific receptor, is downregulated in the gingival epithelium of periodontitis and is associated with inflammation response and periodontitis development." (PMID 36299623, 2022). "FSL-1 was then used as a stimulator to investigate the transcriptional regulation mechanism of ITGB6 suppression associated with periodontitis in the current study." (PMID 36299623, 2022). "However, the regulatory mechanisms underlying the repression of ITGB6 expression by oral biofilm components in periodontitis remain unexplored." (PMID 36299623, 2022). "Furthermore, the reciprocal action of STAT3 and FOXO1 on ITGB6 downregulation was also confirmed by the immunostaining of the inflammatory epithelium associated with periodontitis." (PMID 36299623, 2022). "However, the composition of periodontal bacteria or pathogens that cause periodontitis is complex, and it is difficult to determine the effect of these pathogens on ITGB6 expression." (PMID 36299623, 2022). "Although previous research has confirmed that periodontal bacteria or pathogens may cause ITGB6 repression in periodontitis, limited work has been performed to further investigate the transcriptional mechanism of ITGB6 downregulation in periodontitis." (PMID 36299623, 2022). "Fibroblast-stimulating lipopeptide-1 (FSL-1), an oral biofilm component, promotes an epithelial cell-driven proinflammatory response in periodontitis partially by suppressing ITGB6 expression." (PMID 36299623, 2022). "First, we confirmed the reduction of ITGB6 expression level in periodontitis samples as compared with that in the healthy controls." (PMID 36299623, 2022). "In the present study, we found that the interaction of the transcription factors FOXO1 and STAT3 mediated periodontitis-related lipopeptide FSL-1-induced ITGB6 downregulation in human epithelial cells." (PMID 36299623, 2022). "We identified that the FOXO1–STAT3 interaction may potentially contribute to FSL-1-suppressed ITGB6 expression in the gingival epithelium of periodontitis." (PMID 36299623, 2022). "The aim of the current study was to investigate the transcriptional regulatory mechanism of ITGB6 inhibition by FSL-1 in human epithelial cells (HaCaT and primary human gingival epithelial cells), and to delineate the transcriptional mechanism of ITGB6 suppression in periodontitis." (PMID 36299623, 2022). "Therefore, the interaction of FOXO1 and STAT3 may contribute to periodontitis progression by inhibiting ITGB6 expression." (PMID 36299623, 2022). "Moreover, the absence of ITGB6 was linked to the initiation and progression of periodontitis in a mouse model." (PMID 36299623, 2022). "Therefore, repression of ITGB6 may play a key role in acute inflammation and periodontitis development." (PMID 36299623, 2022). "In the present study, we investigated the transcriptional regulatory mechanism of ITGB6 inhibition by FSL-1 in human epithelial cells (HaCaT and primary human GECs) and delineated the transcriptional mechanism of ITGB6 suppression in periodontitis." (PMID 36299623, 2022). "To confirm the role of FOXO1 and STAT3 and its relation to ITGB6 expression in vivo, we performed immunohistochemistry to detect the expression of ITGB6, FOXO1, and STAT3 using sequencing slices from healthy human gingival tissue and gingival epithelium of patients with periodontitis." (PMID 36299623, 2022).
pneumonia (1 paper, 2012). An acute, acute and chronic, or chronic inflammation focally or diffusely affecting the lung parenchyma, caused by an infection in one or both of the lungs (by bacteria, viruses, fungi, or mycoplasma.). "Itgb6 mouse knock-out mutants exhibit severe pneumonia and an increase in granulocyte recruitment to the lung." (PMID 22905720, 2012).
rhabdomyosarcoma (1 paper, 2024). A rare aggressive malignant mesenchymal neoplasm arising from skeletal muscle. "Rh30 is a rhabdomyosarcoma cell line in which ITGB6 is distributed mainly in the nucleus." (PMID 38814534, 2024).
Sepsis (1 paper, 2022). Sepsis is defined as life-threatening organ dysfunction caused by a dysregulated host response to infection. "Among 5,607 DEGs, Lrg1, Ace2, Itgb6, Hmgb2, Pik3r5, Itgam, Plcb1, Jak2, Vegfa, and Hif1α were associated with the entire course of sepsis-induced myocardial injury, which have been reported previously." (PMID 35721566, 2022).
serous ovarian cancer (1 paper, 2021). "In advanced high-grade serous ovarian cancer, 8 CpGs (ITGB6:cg21105318, cg07896068, cg18437633; NCALD: cg27637873, cg26782361, cg16265707; LAMA3: cg20937934, cg13270625) remained hypermethylated in chemoresistant patients." (PMID 34289901, 2021). "In advanced high-grade serous ovarian cancer, ITGB6, NCALD and LAMA3 hypermethylation indicate chemotherapy resistance and poor prognosis." (PMID 34289901, 2021). "We identified 3 new methylation genes (ITGB6, NCALD and LAMA3) with different chemotherapy outcomes in advanced high-grade serous ovarian cancer." (PMID 34289901, 2021). "In advanced high-grade serous ovarian cancer with complete debulking (N = 37), PFS of 3 candidate CpGs (ITGB6:cg07896068; NCALD: cg27637873, cg16265707) hypermethylation patients was significantly shorter." (PMID 34289901, 2021). "In advanced high-grade serous ovarian cancer with complete debulking, PFS of 3 candidate CpGs (ITGB6:cg07896068; NCALD:cg27637873, cg16265707) hypermethylation patients was significantly shorter." (PMID 34289901, 2021).
squamous cell carcinoma (1 paper, 2015). A carcinoma arising from squamous epithelial cells. "These constructs were then transfected into a non-human squamous cell carcinoma cell line (293T) and human OSCC cell line (TCA8113) to determine the contribution of each region of the ITGB6 promoter on gene expression activity." (PMID 25816241, 2015).
taurodontism (1 paper, 2023). Taurodontism is a dental anomaly characterized by an elongated pulp chamber, displaced toward the apical floor of the tooth with no constriction at the level of the cemento-enamel junction, and short roots. "Of six affected families and eight ITGB6 variants that have been reported, our patient was the only one with taurodontism." (PMID 37041139, 2023).
Ureteral obstruction (1 paper, 2019). Obstruction of the flow of urine through the ureter. "Otherwise, many of these genes, such as Agt, Ccl12, Col3a1, Dcn, Itgb6, and Thbs2, were temporarily changed in these MSLCs expanded from the left kidney at only 7 days after ureteral obstruction, but the changes of Ccl3 and Cxcr4 were constantly observed during the 14 days of follow-up." (PMID 30949209, 2019).
viral infections (1 paper, 2012). "Qivr2-2 contains two candidate genes, Itgb6 (integrin beta 6) and Ifih1 (interferon induced with helicase C domain 1), with known functions in the host defense to viral infections." (PMID 22905720, 2012).
tumor (62 papers, 2012 to 2025). "We analyzed the correlation of FN1, ITGA4, ITGA5, ITGAV, ITGB1, ITGB3 and ITGB6 with disease status, risk of tumor recurrence according to the 2015 American Thyroid Association guidelines, and patient outcome." (PMID 40423510, 2025). "ITGB6 expression showed significant associations with tumor size (P=0.030), pathological grading (P=0.013), location (P=0.031), N stage (P=0.002), and clinical stage (P=0.002)." (PMID 38344200, 2024). "Overall, our findings indicate that the expression level of ITGB6 is associated with tumor progression and invasiveness in OSCC (e.g., perineural invasion)." (PMID 38890650, 2024). "ITGB6 expression was significantly associated with pathological grading (P=0.013), tumor size (P=0.030), location (P=0.031), N stage (P=0.002), TNM stage (P=0.002), positive lymph node rate (P=0.002), and survival status (P<0.001)." (PMID 38344200, 2024). "There was a significant decrease in Ki67 staining upon integrin β6 deletion within the tumor tissues, indicating reduced number of proliferative cells and tumor growth in CAC caused by ITGB6 knockout." (PMID 37223685, 2023). "In line with previous findings, we demonstrate here that ITGB6 expression was positively associated with SKCM tumor stage." (PMID 34660316, 2021). "ITGB6 was considered to be a prognostic indicator as its increased expression in tumor tissues was significantly associated with the prognosis of patients in various tumors." (PMID 34796117, 2021). "DFS was significantly associated with positive lymph nodes (p = 0.047), a tumour size ≥2 cm (p = 0.043), perineural infiltration (p = 0.006) and the staining of ITGB6 (p < 0.001) and SFN (p = 0.032)." (PMID 32376891, 2020). "In the model we studied, ITGB6 was highly expressed in a low-risk population, possibly early in tumourigenesis, enhancing tumor cell adhesion and the ECM barrier, and may act as a protective factor in the risk stratification of BLCA mortality." (PMID 36267977, 2022). "Moreover, ITGB6 expression in tumor tissues was also associated with tumor N stage." (PMID 34796117, 2021). "Moreover, serum ITGB6 expression was associated with ITGB6 expression in tumor tissues." (PMID 34796117, 2021). "Additional tumor-associated receptors in HNSCC include integrin beta-6 (ITGB6), a component implicated in tumor invasiveness and frequently overexpressed in HNSCC, where its expression is associated with poor clinical outcomes." (PMID 41375018, 2025). "The ability of an RGD peptide or an anti‐integrin αvβ6 antibody to block the adhesion of tumour cells expressing ITGB6 indicates that this interaction can be targeted." (PMID 40488391, 2025). "This interaction was greatly reduced by silencing ITGB6 in the tumour cells and was integrin β6 dependent under both static and flow conditions." (PMID 40488391, 2025). "This led to the discovery of 36 putative tumor-surface antigens, such as integrin beta-6 (ITGB6), fibroblast growth factor receptor-4 (FGFR4), and ectonucleotide pyrophosphatase/phosphodiesterase 1 (ENPP1)." (PMID 39755633, 2025). "Plasma elevation of Itgb6 has been proposed as a novel serum tumor marker, but its relevance in acute brain injury warrants further investigation." (PMID 40536110, 2025). "The growth inhibitory effect was correlated to the expression of NECTIN1, NECTIN2, and ITGB6 by the tumor cell lines." (PMID 40955425, 2025). "To validate the observed accumulation of integrins on the tumor cell surface, we focused on the most enriched integrins upon AP2 loss, namely ITGB1, ITGB6, ITGA2, and ITGA3." (PMID 40050266, 2025). "A stepwise focusing through the three‐dimensional complex of an ITGB6‐expressing tumour cell (green) attached to a fibronectin‐expressing endothelial cell (red) confirmed the interaction of both molecules (yellow arrows)." (PMID 40488391, 2025).
tumor (continued). "The sigvotatug vedotin construct links an ITGB6-directed monoclonal antibody to the cytotoxic payload MMAE via a cleavable linker, enabling selective internalization and microtubule disruption in ITGB6-expressing tumor cells." (PMID 41375018, 2025). "Multiple investigations have indicated that the activation of Rac1 is prompted through its interaction with ITGB6, one of its downstream effectors, thereby augmenting the migratory and invasive capabilities of tumor cells." (PMID 38344200, 2024). "Through the STRING interaction, subcellular localization and pathway entries provided by EZCancerTarget, we learned that ITGB6 is structurally and functionally connected to the tumor microenvironment's proteoglycan components." (PMID 36183137, 2022). "Another factor, Ets-1, is found to be up-regulated in the tumour process, wherein it boosts the ITGB6 expression and cell invasions." (PMID 36293202, 2022). "Seven ECMGs (i.e. LAMB3, LAMA3, ITGB6, ITGB4, ITGA2, LAMC2, and COL11A1) were identified to be hub genes of PAAD, which were obviously up-regulated in PAAD and considerably linked to tumor stage as well as prognosis." (PMID 36311789, 2022). "We matched the expression profiles of three prognostic genes in the TCGA-BLCA and GSE7476 datasets and found that both ITGA5 and ITGA7 were significantly reduced in tumor samples; while ITGB6 was notably overexpressed in the BLCA group (all P< 0.05)." (PMID 36267977, 2022). "In this work, the data mining of PDAC scRNA-seq data revealed that ITGA2, ITGA3, ITGB4, and ITGB6 were dominantly expressed in tumor cells." (PMID 35719923, 2022). "These liposomes successfully delivered the antibodies into ITGB6-positive tumour cells and provided an efficient strategic approach for targeted drug delivery." (PMID 36293202, 2022). "PD-L1 was shown to directly interact with β6 integrin (ITGB6), enhance tumor cell proliferation, alter glucose metabolism, and overall promote tumor progression." (PMID 34065396, 2021). "The results showed that ITGB1 (4/10), ITGB3 (6/10), ITGB5 (6/10), and ITGB6 (5/10) protein levels were increased in tumour tissues compared to adjacent tissues." (PMID 34709754, 2021). "As one of the key adhesion molecules on cell surface, ITGB6 was found to be involved in almost every step during tumor metastasis." (PMID 34796117, 2021). "Among the patients with tumor recurrence, 4 of them had elevated serum ITGB6 levels, accompanied with increased tumor burden." (PMID 34796117, 2021). "In future studies, we want to establish a xenograft tumor model in nude mice bearing ITGB6-ko iCCA cells." (PMID 34208313, 2021). "We found that stratification of the HER2+ tumor samples by ITGB6 mRNA levels produced significant separation of the groups based on disease‐free survival with a hazard ratio (HR) of 2.9 (0.9–8.9); log rank P = 0.05." (PMID 27184932, 2016). "ITGB6, which mediates the interactions between adjacent cells and between cells and extracellular matrix, is down-regulated during tumor progression." (PMID 22328933, 2012). "Furthermore, ITGB6 expression was significantly elevated in liver metastases compared to corresponding primary tumours from the same patients, suggesting an enrichment of β6‐expressing cells in metastatic sites." (PMID 40488391, 2025). "Similarly, mesenchymal gene ITGB6 is significantly downregulated in good-prognosis tumours (log2fc = −2.22), underscoring the role of mesenchymal transition in tumour aggressiveness." (PMID 41007296, 2025). "In addition to FN1, high risk of tumor recurrence was associated with higher expression of ITGAV, ITGB1 and ITGB6." (PMID 40423510, 2025). "Expression of ITGB6 in CRC tumour cells closely correlated with their adhesion to EC." (PMID 40488391, 2025). "Additionally, our experiments using cell transfection and Transwell invasion/migration assay demonstrate that si-ITGB6 can inhibit tumor invasion and metastatic abilities." (PMID 38344200, 2024).